CSF1R (colony stimulating factor 1 receptor)
Diseases named in the same sentence as CSF1R in open-access papers (continued):
Sharing a sentence is not in itself a finding about the gene and the disease.
neurological disorders (continued). "Thus, therapeutic agents inhibiting CSF1R in the microglia could be promising in the treatment of neurological diseases." (PMID 33192177, 2020). "Depletion of microglia, via blockade of colony-stimulating factor 1 receptor (CSF1R) signaling, led to increased viral replication accompanied by more severe neurological disease and heightened mortality." (PMID 31798586, 2019). "In contrast, microglia replacement, which efficiently delivers healthy cells via the microglia niche generated by colony-stimulating factor 1 receptor (CSF1R) inhibition, may offer a valuable therapeutic strategy for various neurological diseases." (PMID 40818647, 2025). "Microglia from non-neurological disease controls and individuals with ASD in both the snRNA-seq and scRNA-seq datasets expressed characteristic microglial markers such as P2RY12, CX3CR1, AIF1, CSF1R and IL18." (PMID 35739273, 2022). "Thus, microglial CSF1R is highlighted as emerging targets for disease-modifying therapy in ALSP and other neurological disorders." (PMID 34867307, 2021). "Furthermore, peripheral levels of CSF1, a CSF1R ligand, correlate with CSF1R levels in the CNS, and peripheral administration of CSF1 improves neurological disorders." (PMID 34512619, 2021).
brain disease (8 papers, 2011 to 2025). "The therapeutic potential of modulating CSF1R signaling in brain diseases has been proposed on several levels." (PMID 40659845, 2025). "The importance of understanding the effects of microglial depletion in the human brain is increasingly relevant as multiple clinical trials are focusing on CSF1R inhibitors to deplete microglia in brain disease." (PMID 35713703, 2022). "The up-regulation of M-CSF and its receptor CSF-1R has been reported in brain disease, as well as in diabetic complications; however, the mechanism is unclear." (PMID 21266043, 2011). "Also, in vitro biochemical experiments show that pathogenic CSF1R missense variants act dominantly on CSF1R signaling, and parents of bi-allelic patients with heterozygous haploinsufficient CSF1R variants have not been noted to develop brain disease." (PMID 35713703, 2022). "Overall, our results highlight the challenges of targeting the CSF1R/IL34 axis in the systemic and central compartments, important for framing any therapeutic effort to tackle microglia/macrophage numbers during brain disease." (PMID 33162994, 2020). "These alterations, typically found in different situations of brain disease and pathology, suggest that microglia from CMVMJD135 + vehicle and CMVMJD135 + PLX3397 mice are similar and showed an activation profile, which was not dependent on CSF1R signaling." (PMID 35805106, 2022).
hematologic malignancies (6 papers, 2016 to 2024). "Many ongoing clinical trials have tested humanized monoclonal anti‐CSF1R antibodies and CSF1R inhibitors can be a method of inhibiting TAMs in advanced metastatic solid cancer and hematological malignancies." (PMID 35593325, 2022). "More importantly, CSF-1R blockade prevents the generation of LAM in a variety of hematologic malignancies." (PMID 28031823, 2016). "Therefore, inhibition of CSF-1R has emerged as a rational therapeutic strategy in many solid tumors and hematologic malignancies." (PMID 28031823, 2016).
metabolic disease (4 papers, 2019 to 2025). A congenital disorder (due to inherited enzyme abnormality) or acquired (due to failure of a metabolically important organ) disorder resulting from an abnormal metabolic process. "A better understanding of the tissue-specific effects of CSF1R inhibition on immune cells and glucose homeostasis is crucial for the development of targeted immune-modulatory treatments in metabolic disease." (PMID 37792013, 2023).
autosomal dominant disease (3 papers, 2019 to 2023). Autosomal dominant form of disease. "Since HDLS was identified as a rare autosomal dominant disease caused by a mutation of the colony stimulating factor 1 receptor (CSF1R) gene located on chromosome 5 (5q32), more than 70 pathogenic mutations have been reported in both hereditary and sporadic cases." (PMID 31093799, 2019).
bacterial infection (3 papers, 2020 to 2023). "In addition to its regulation on the function and number of corneal ResMφ at a steady-state, our data demonstrated that miR-183/96/182 imposes a significant impact on the dynamics of Csf1r-EGFP+ myeloid-derived MPS cells, which include both ResMφ and DCs, in response to bacterial infection." (PMID 33208381, 2020).
immune diseases (3 papers, 2018 to 2025). "Furthermore, several key genes (e.g., Csf1r, Ifnb1, IL-20, IL-22, IL-24, Jhdm1d, Csf1r, Ifnb1, IL-20, IL-22, IL-24, and Tgfb2 that regulate sex differences in immune diseases) were discovered." (PMID 30246031, 2018). "Therefore, we hypothesize that aberrant expression or functional dysregulation of CSF1R may initiate or exacerbate immune dysfunction in MN." (PMID 40539070, 2025).
inflammation (3 papers, 2017 to 2023). Aberrant reaction of the microcirculation characterized by movement of fluid and leukocytes from the blood into extravascular tissues. "Our previous study showed that long-term exposure to low-dose MC-LR increased chronic colorectal inflammation, fibrosis, and barrier damage through activating the CSF1R/Rap1b signaling pathway." (PMID 37756005, 2023). "In an acute LPS driven CNS inflammation model, we identified CSF1R-dependent microglial proliferation as a potential deleterious neuroinflammatory mechanism." (PMID 33097690, 2020).
skeletal dysplasia (3 papers, 2020 to 2022). Any Mendelian diseases that affects growth and development of the skeleton. "For instance, bi-allelic Csf1r deficiency in mouse was reported to cause brain development abnormalities and sclerosing skeletal dysplasia which leads to death within 6 weeks." (PMID 33816491, 2021). "Pathogenic variants in CSF1R could lead to autosomal dominant adult-onset leukoencephalopathy with axonal spheroids and pigmented glia or autosomal recessive skeletal dysplasia." (PMID 33816491, 2021).
adenocarcinoma (2 papers, 2018 to 2022). A common cancer characterized by the presence of malignant glandular cells. "In a multivariable Cox model, the P value for a prognostic interaction between CSF1R expression (low–moderate vs. high) and smoking status (never- vs. ever-smoker) was not significant (P for interaction = 0.12) after adjusting for the pathological stage of the adenocarcinoma." (PMID 30065206, 2018).
retinal disorder (2 papers, 2018 to 2023). Any disease or disorder of the retina. "Microglial depletion by the colony-stimulating factor 1 receptor (CSF1R) inhibitor PLX3397 suppresses retinal neovascularization in oxygen-induced retinopathy." (PMID 37085894, 2023).
haematopoietic cancers (1 paper, 2021). "In contrast, CSF1R mutations accumulate in the negative regulatory motifs (a c-Cbl ubiquitin ligase binding motif) in the receptor tail, leading to the overactivation of the receptor in various haematopoietic cancers." (PMID 33806614, 2021).
kidney diseases (1 paper, 2021). "Although the definite effects of CSF1R in macrophage recruitment and proliferation, the role of CSF1R inhibitors and neutralizing antibodies have not been tested in clinical trials to treat kidney diseases." (PMID 34093584, 2021).
peripheral neuropathy (1 paper, 2019). A disorder affecting the peripheral nervous system. "Whether peripheral neuropathy belongs to CSF1R-related spectrum is still pending and needs further investigation with more patients enrolled and longer follow-up." (PMID 31827782, 2019). "Indeed, whether CSF1R-related spectrum includes peripheral neuropathy deserves longer follow-up with more patients enrolled as well as further study in animal models." (PMID 31827782, 2019).
CSF1R also shares sentences with these, for which no sentence is quoted: pertussis (22 papers); amyotrophic lateral sclerosis (9); Parkinsonism (7); Insulin resistance (5); bone cysts (4); psychiatric disorder (4); acute kidney injury (3); bladder cancer (3); Dystonia (3); fibrosis (3); Huntington disease (3); leukocytosis (3); mammary adenocarcinoma (3); nasal polyps (3); pancreatic adenocarcinoma (3); parasitic infection (3); Peripheral T Cell Lymphoma (3); Ataxia (2); autoimmune encephalitis (2); cardiovascular disease (2); cerebral amyloid angiopathy (2); cerebral arteriopathy with subcortical infarcts and leukoencephalopathy (2); cerebral small vessel disease (2); cognitive disease (2); cutaneous melanoma (2); cyst (2); developmental delay (2); encephalomyelitis (2); head and neck squamous cell carcinoma (2); hereditary spastic paraplegia (2).
A further 136 diseases each share a sentence with CSF1R in 2 papers or fewer.